OPLAH (5-oxoprolinase, ATP-hydrolysing)
Description:
Catalyzes the cleavage of 5-oxo-L-proline to form L-glutamate coupled to the hydrolysis of ATP to ADP and inorganic phosphate.
Synonyms: 5-OPase; OPLA; OPLAHD
Tractability: PROTAC: ubiquitination databases record sites on it; its protein half-life has been measured.
Gene: Protein-coding gene on chromosome 8 (144,051,265 to 144,064,091, reverse strand). Ensembl gene ENSG00000178814.
Subcellular location: Cytoplasm, cytosol
Subcellular location (Human Protein Atlas): Nucleoli fibrillar center
Pathways (Reactome):
Disease: Defective OPLAH causes OPLAHD
Metabolism: Glutathione synthesis and recycling
Gene Ontology:
Molecular function: protein binding; 5-oxoprolinase (ATP-hydrolyzing) activity; catalytic activity; hydrolase activity
Biological process: glutathione catabolic process
Cellular component: cytosol
Genetic constraint (gnomAD): Loss-of-function variants: 105 observed, 106.2 expected, observed/expected ratio (o/e) 0.99, 90% interval 0.84 to 1.16. The synonymous counts are far from expectation, so gnomAD's model fits this gene poorly and the ratio says little. Missense variants: 1,900 observed, 1,689.9 expected, observed/expected ratio (o/e) 1.12, 90% interval 1.08 to 1.17. Synonymous variants: 874 observed, 723.75 expected, observed/expected ratio (o/e) 1.21, 90% interval 1.14 to 1.28.
Homologues: Orthologues: chimpanzee OPLAH (99% identical), macaque OPLAH (98% identical), dog OPLAH (95% identical), rat Oplah (94% identical), mouse Oplah (93% identical), pig OPLAH (93% identical), guinea pig OPLAH (91% identical), tropical clawed frog oplah (72% identical), zebrafish oplah (69% identical), Drosophila melanogaster CG4752 (61% identical), Caenorhabditis elegans Y38F2AR.12 (56% identical).
Diseases named in the same sentence as OPLAH in open-access papers:
OPLAH is named in the same sentence as 25 diseases in open-access papers, as found by Europe PMC text mining. Sharing a sentence is not in itself a finding about the gene and the disease. The quoted sentences say what the papers report.
adenoma (2 papers, 2021 to 2025). A neoplasm arising from the epithelium. "These authors found that OPLAH alone and/or a combination of a few methylated DNA markers (ARHGEF4, LRRC4, ANTXR1, PITX1) can discriminate adenomas and CRC in LS patients." (PMID 34201893, 2021).
lung carcinoma (2 papers, 2022). "Recently, OPLAH was identified as one of the biomarkers that have been patented for the diagnosis of lung cancer (patent number: US 11028447 B2) and CRC (patent number: US 11078539 B2)." (PMID 35054365, 2022).
esophageal cancer (1 paper, 2020). A primary or metastatic malignant neoplasm involving the esophagus. "Based on TCGA database and literature search, we analyzed the methylation of KCNA3, USP44, OPLAH and SMTN in esophageal cancer." (PMID 32266120, 2020).
hypogonadism (1 paper, 2022). A disorder characterized by decreased function of the gonads. "The increase of 5-oxoprolinase (OPLAH) in hypogonadism might reflect a deficiency in the biosynthesis of glutathione, which is an important scavenger for reactive oxygen species in man." (PMID 35663320, 2022).
Lynch syndrome (1 paper, 2020). An autosomal dominant hereditary neoplastic syndrome characterized by the development of colorectal carcinoma and a high risk of developing endometrial carcinoma, gastric carcinoma, ovarian carcinoma, renal pelvis carcinoma, and small intestinal carcinoma. "One of their patents, US 10,370,726 B2, is a patent granted for the use of OPLAH, among other genes, to detect CRC in individuals younger or older than 50 years old or in Lynch Syndrome patients." (PMID 32380793, 2020).
Renal cyst (1 paper, 2024). A fluid filled sac in the kidney. "We found that multiple genes encoding enzymes in the γ-glutamyl cycle were highly downregulated in renal cysts, including γ-glutamyl transferase (GGT1, −14×), dipeptidase 1 (DPEP1, −32.5×), aminopeptidase N (ANPEP, −12×) and 5-oxoprolinase (OPLAH, −2.6×)." (PMID 39000280, 2024).
steatosis (1 paper, 2021). Increased lipid within the cytoplasm of cells. "Low expression of OPLAH, as seen in both steatosis and NASH, is associated with accumulation of 5-oxiproline and increased oxidative stress in in vivo and in vitro studies." (PMID 34869521, 2021). "Two selenoprotein genes (GPX2 and GPX3) encompassed in the “glutathione metabolism” pathway had higher expression, and one gene had lower expression (OPLAH) in steatosis, suggesting an increase in glutathione utilisation." (PMID 34869521, 2021).
cancer (5 papers, 2015 to 2025). A tumor composed of atypical neoplastic, often pleomorphic cells that invade other tissues. "As an example, the hypermethylation of the OPLAH dDMR was associated with the upregulation of OPLAH expression in SKCM cancer cell lines and HG-6-64-1 drug sensitivity." (PMID 37558831, 2023). "Despite a paucity of information on OPLAH methylation in cancer, several patents have been filed for its applicability in cancer detection." (PMID 35054365, 2022). "While KIT mutations are well-known drivers of GIST, tissue-specific genes such as the serine/threonine protein kinase TESK1, the myelin regulatory factor MYRF, as well as the 5-oxo-L-prolinase OPLAH or the zinc influx transporter SLC39A9 have not been associated with cancer before." (PMID 26102504, 2015).
tumor (5 papers, 2022 to 2025). "In addition, this epigenetic regulation of OPLAH expression was also demonstrated in primary tumour samples." (PMID 37558831, 2023).
OPLAH also shares sentences with these, for which no sentence is quoted: 5-Oxoprolinuria (2 papers); 5-oxoprolinase deficiency (1); colon cancer (1); colorectal cancer (1); glioblastoma (1); heart failure (1); Hypoglycemia (1); infection (1); Infertility (1); legionellosis (1); metabolic acidosis (1); metabolic disease (1); myocardial infarction (1); nasopharyngeal carcinoma (1); ovarian carcinoma (1); pancreatic cancer (1).